MUC1 (mucin 1, cell surface associated)
Diseases named in the same sentence as MUC1 in open-access papers (continued):
Sharing a sentence is not in itself a finding about the gene and the disease.
colon carcinoma (continued). "In the present study, we found MUC1 and CIN85 overexpressed in benign as well as malignant colon tumors with the highest co-expression levels observed in advanced clinical grades and primarily in colon adenocarcinomas with lymph node positivity and metastases." (PMID 25675408, 2015). "In breast and colon cancers, HRG stimulation facilitates the binding between MUC1-CT and γ-catenin, allowing MUC1 to function as a vehicle for γ-catenin nuclear translocation." (PMID 25261375, 2014). "Recently, it has been reported that MUC1, which is also identified as a hypoxia-inducible mucin, could promote autophagy, providing a survival advantage in the low glucose-stressed microenvironment through the suppression of glucose deprivation-induced increases of ROS levels in colon cancer." (PMID 22970168, 2012). "Patients with a very early stage of colon cancer (Tis-T1) had also a statistically significant difference regarding total MV counts, TF-positive MVs, EMVs, combined EMV/TF MVs, MUC-1-positive MVs, and MUC-1/TF combined MVs (all p < 0.001)." (PMID 38792021, 2024). "In human colon cancer cell lines, CBL demonstrated co-localization with CIN85 and MUC1." (PMID 39130630, 2024). "In contrast to colon carcinomas, MUC1 is not present at significantly high levels in healthy human colon." (PMID 28588132, 2017). "To further confirm the role of MUC1 O-glycosylation in MUC1-mediated cell resistance to anoikis, we stably transfected human colon cancer SW620 cells, which express high level of MUC1, with shRNA C1GT and control shRNA and generated C1GT stably suppressed cells." (PMID 28725490, 2017). "MUC1 immunohistochemical stain was shown to demonstrate reverse polarity—peripheral membranous staining toward the stroma—of PDC and TB in treatment‐naïve colon cancer." (PMID 27165693, 2016). "Co-expression of MUC1 and CIN85 in lymph node positivity and distant metastasis in colon cancer." (PMID 25675408, 2015). "Thus, our study finds that MUC1, CIN85 and Cbl are overexpressed and co-localize in colon cancer cells." (PMID 25675408, 2015). "In humans, colon carcinoma cells, but not normal colonic epithelia, express MUC1, and the level of MUC1 in colon carcinoma tissues correlates with the stage of the disease." (PMID 23028615, 2012). "Additionally, MUC1 inhibits hypoxia-induced cell death and suppression of HIF-1α stability through reducing intracellular ROS and prolyl hydrolase-3 (PHD-3) activity in colon cancer cells." (PMID 33836774, 2021). "We generated MUC1-transfected mouse colon carcinoma SL4 cells (SL4-MUC1 cells), which are highly tumorigenic and metastatic in C57BL/6 (B6) mice, and control cells transfected with the empty vector (SL4-mock cells) that exhibited similar growth behavior to the SL4-MUC1 cells." (PMID 23028615, 2012). "In vitro studies using colon tumor human cell lines have indicated that MGL is the receptor that recognizes and binds to MUC1–Tn antigen;33 however, the role of the interaction between the MUC1‐Tn antigen and antigen‐presenting cells in the biology of CAC tumors is unknown." (PMID 40033767, 2025). "First, to assess toxicity and the impact of MUC-1 aptamer, two cell lines MUC-1 positive (HT29 and C26, human and murine colon cancer) and one cell line MUC-1 negative (CHO, Chinese hamster ovary) were used." (PMID 38399238, 2024). "The cytotoxicity study on MUC1 positive HT29, SW480 colon cancer cells and MUC1 negative CHO cells indicated that the designed potent hybrids had a higher toxicity on HT29 and SW480 cell lines than on CHO cells." (PMID 37376161, 2023). "The MAbs reacted with synthetic MUC2 VNTR peptides but not synthetic MUC1 or MUC3 VNTR peptides, and showed specific reactivity in Western blotting with a high molecular weight protein produced by the LS174T colon carcinoma cell line." (PMID 8512804, 1993).
prostate carcinoma (83 papers, 2004 to 2025). A carcinoma that arises from epithelial cells of the prostate gland. "Its overexpression in metastatic renal cell carcinoma (RCC) and prostate carcinoma is associated with poor prognosis, therefore MUC1 has been used in different types of cancer vaccines." (PMID 28116088, 2017). "In summary, MUC1 expression is associated with extracapsular extension and higher Gleason score in men undergoing radical prostatectomy for clinically localized prostate cancer." (PMID 27846218, 2016). "This pattern of heterogeneous expression is consistent with MUC1's association with our prostate cancer stem-like cells." (PMID 27825118, 2016). "The results presented here demonstrate, for the first time, a significantly reduced frequency in blood DNA of the MUC1 3506G allele in hereditary prostate cancer compared to population, BPH and sporadic prostate cancer samples." (PMID 19578514, 2008). "With functions including protection, adhesion and signaling, MUC1 has been implicated in prostate cancer." (PMID 19578514, 2008). "That both under and over expression of MUC1 is associated with prostate cancer death suggests that the level of VNTR-containing MUC1 variants is regulated in normal cells to maintain a precise level." (PMID 19578514, 2008). "The group with Gleason score ⩾7 and MUC-1 lower or higher than normal had a 17 (HR=17.1 (95%CI=2.3–128)) times higher risk of prostate cancer death compared with tumours with Gleason score <7 and normal MUC-1 intensity." (PMID 17726465, 2007). "Men with a Gleason score ⩾7 and MUC-1 deviating from the normal had a 17 (RR=17.1 95% confidence interval=2.3–128) times higher risk to die in prostate cancer compared with men with Gleason score <7 and normal MUC-1 intensity." (PMID 17726465, 2007). "These competing mechanisms provide possible explanations for our findings that both over- and underexpressions of MUC-1 increases the risk of prostate cancer progression." (PMID 17726465, 2007). "It was suggested that MUC1, a mucin detected in an important proportion of prostate cancers, was associated with a decrease of cell to cell or cell to extracellular matrix interactions, by masking cellular adhesion molecules." (PMID 14760390, 2004). "MUC1 was shown to induce BRN2, an NEPC-associated transcription factor, through MYC-mediated mechanism, and silencing MUC1 caused suppression of BRN2.This study highlights the significance of MUC1 in prostate cancer lineage plasticity, making it an attractive target for therapeutic inter-vention." (PMID 34298815, 2021). "Previous reports have implicated MUC1 as a potential prognostic biomarker prostate cancer." (PMID 27846218, 2016). "Given its association with adverse pathology, MUC1 could have some role in selecting patients for definitive treatment who otherwise have features of low risk prostate cancer." (PMID 27846218, 2016). "Differential expression of MUC1 variants 1 and 2 is thus implicated in prostate cancer." (PMID 19578514, 2008). "Although controlling PSA levels could attenuate the association between MUC-1 and prostate cancer death, it is unlikely that it would fully explain the relationship." (PMID 17726465, 2007). "In the present study, we test the hypothesis that altered tumour expression of MUC-1 is associated with prostate cancer death." (PMID 17726465, 2007). "The risk of dying of prostate cancer was four times higher among those with a higher (3.9 (95% confidence interval (CI)=1.1–14)) or lower (3.8 (95%CI=1.1–13)) MUC-1 expression than among those with an MUC-1 expression within the normal range." (PMID 17726465, 2007).
prostate carcinoma (continued). "The potential for MUC1 to predict adverse reclassification has been suggested by a demonstration that MUC1 expression independently predicted upstaging and upgrading in low risk prostate cancers incidentally discovered at the time of transurethral resection of the prostate." (PMID 27846218, 2016). "Therefore, we test the hypothesis that altered expression of MUC-1 is associated with prostate cancer progression." (PMID 17726465, 2007). "Overexpression of C2GNT1 results in altered O-glycosylation of prostate-specific antigen (PSA), prostatic acidic phosphatase (PAP) and mucin 1 (MUC1) in prostate cancer cells." (PMID 38274327, 2024). "Another oncogene driving NET of prostate cancer is Mucin 1 (MUC1), whose amplification has been observed in ~30% of NEPC patients in comparison to 6% of CRPC patients." (PMID 38391963, 2024). "Initially studied as a cancer-associated serum antigen (CASA) in PCa, the close relationship between MUC1 and prostate cancer has gained increasing attention with further research." (PMID 39491020, 2024). "MUC1 has also been shown to be an independent prognostic biomarker for PCa-associated death and tumor proliferation (for MUC1-positive DU145 and PC3 prostate cancer cell lines)." (PMID 39594740, 2024). "Researchers have characterized MUC1 with O-glycans, and subsequently found that in prostate cancer, the O-glycans on MUC1 are mainly core 2 structure, followed by fucosylated types of core 2 structure." (PMID 37894512, 2023). "It is also known that MUC1 gene expression in prostate cancer cells is inhibited by the androgen receptor (AR)." (PMID 36980530, 2023). "A study found that the anti-Muc1 CAR T cells can selectively kill prostate cancer cells which expressed Muc1." (PMID 35508696, 2022). "An adenovirus vaccine targeting prostate‐specific antigen, brachyury, and MUC1 together was also used in Phase I clinical trials in prostate cancer, ending with good tolerance." (PMID 35102706, 2022). "Some examples of these nanomaterials are the MUC1 aptamers to recognize MUC1 proteins on cell surfaces with silver nanoprisms and gold nanoparticles to detect the prostate-specific antigen for prostate cancer." (PMID 35454775, 2022). "In prostate cancer PC-3 cells, arctiin induced cell detachment and lowered cell numbers through modulation of antiadhesion molecule MUC-1." (PMID 35214097, 2022). "PPI was recently found to inhibit castration-resistant prostate cancer growth by reducing p65 and MUC1 protein levels and downregulating lncRNA HOX transcript antisense RNA (HOTAIR) expression." (PMID 35154471, 2022). "MUC1 is normally expressed on the surface of most glandular epithelia but overexpression of MUC1 can be found on many tumors, such as lung, pancreatic, breast, ovarian, and prostate cancers." (PMID 35891256, 2022). "For example, the mucin 1 (MUC1) antigen is expressed in prostate cancer cells, but nearly all metastatic cancer cells lack HLA-I molecules; thus, metastatic cancer cells cannot be specifically recognized by T cells." (PMID 35725570, 2022). "MUC1/Y, in particular, was found to be highly expressed in breast, ovarian, and prostate cancer cells." (PMID 34452200, 2021). "Of note was PI3K family members: PIK3C2G, PIK3CA, PIK3CB, PIK3R4, Mucin family members: MUC1, MUC4 and MUC6 and other prostate cancer associated genes such as SMAD4, SOX9 and SPOP7,9,40,41." (PMID 32796921, 2020). "In a Phase 1/2 trial of human prostate cancer, Tn-MUC1 DC vaccination was able to induce a significant CD8+ T cell response." (PMID 33260328, 2020). "In preclinical studies in a prostate cancer model, even combined targeting of two antigens, MUC1 and PSCA, was insufficient to eliminate the tumor." (PMID 32357417, 2020). "In prostate cancer, cancer-associated antigens PSA, PSMA, PAP, PSCA, MUC1 and PAGE/GAGE have been used to stimulate T cell-mediated immunity." (PMID 31303962, 2019).
prostate carcinoma (continued). "A MUC1-C–specific HLA-A24+ T-cell line derived from a patient with prostate cancer was stimulated using its specific MUC1 peptide and DCs treated with 0, 0.25 or 1.0 μM of epacadostat." (PMID 27192116, 2016). "In prostate cancer, as in many malignancies, MUC1 and other glycoproteins show truncated O-glycans and an increase in sialylation." (PMID 27846218, 2016). "The mucin 1 (MUC1) oncoprotein is highly expressed in human prostate cancers with aggressive features." (PMID 27830724, 2016). "Mass spectrometric determination of MUC1-transfected prostate cancer cell line C4-2B4, revealed that the most prominent O-glycan on MUC1 was the non-sialylated and non-fucosylated core 2 oligosaccharide Galβ3/4GlcNAcβ6." (PMID 27754373, 2016). "We analyzed the MUC1 glycoproteins of the prostate cancer cells for O-glycosylation by western blotting." (PMID 23165940, 2013). "A similar study also demonstrated that high levels of AR inhibited the production of MUC1 and AR-negative prostatic cancer cells expressed high level of MUC1." (PMID 23451223, 2013). "A recent report showed that the expression of MUC1 gene in prostatic cancer cells is inversely regulated by the androgen receptor (AR) in a dose-dependent manner." (PMID 23451223, 2013). "Our results taken together with this observation suggest that the modification of MUC1 in C2GnT-expressing prostate cancer cells with bulky poly-N-acetyllactosamine moieties reduces their adhesiveness, thereby attenuating the NK cell-cancer cell interaction." (PMID 23165940, 2013). "In our study, we found that RWPE-1 cells, an AR positive cell line, expressed MUC1, a phenomenon contrary to the proposed mode of action of AR in prostatic cancer cells." (PMID 23451223, 2013). "We have previously shown that MUC1 is modified by poly-N-acetyllactosamine on its O-glycan residues in C2GnT-expressing prostate cancer cells." (PMID 23165940, 2013). "The aberrant expression of MUC1 has been correlated with recurrence and life expectancy for prostate cancer." (PMID 18446242, 2008). "Altered expression levels and localization, as well as delayed tumor formation being observed in knockout mice, implicate MUC1 in cancers such as prostate cancer." (PMID 19578514, 2008). "Of the 43 patients that had an MUC-1 intensity close to normal tissue (102.5–106), three (7%) died of prostate cancer, compared with 34 (23%) of the 152 patients that deviated from the normal MUC-1 intensity." (PMID 17726465, 2007). "As the accuracy of MUC-1 alone or together with the Gleason Score in predicting prostate cancer progression was low, we conclude that its use as a single biomarker in clinical decision making is limited." (PMID 17726465, 2007). "We further examined the accuracy of using MUC-1 as a test for prostate cancer progression and found that using MUC-1 alone resulted in a reasonable sensitivity but poor specificity." (PMID 17726465, 2007). "The recombinant mva called TG4010 expresses both Muc1 (a higher-molecular-weight mucin that is overexpressed in most carcinomas, including prostate carcinoma) and il-2." (PMID 18080016, 2007). "The sensitivity for MUC-1 as predictor of lethal prostate cancer was 0.91, whereas the specificity was 0.25." (PMID 17726465, 2007). "In this population-based cohort of men with localised prostate cancer cases (T1a-b, Nx, M0), we found that MUC-1 expression at diagnosis was a predictor of prostate cancer death." (PMID 17726465, 2007). "We modelled prostate cancer-specific death as a function of MUC-1 levels accounting for age, Gleason grade and tumour extent, and calculated age-adjusted and multivariate adjusted hazard ratios (HR)." (PMID 17726465, 2007). "In summary, these data show that MUC-1 is an independent prognostic marker for prostate cancer death." (PMID 17726465, 2007). "In prostate cancer, overexpression of MUC-1 in tissue has been correlated both with higher Gleason grade and advanced tumour stage." (PMID 17726465, 2007).
prostate carcinoma (continued). "We further assessed the ability of MUC-1 expression (deviating from the normal range) to correctly classify prostate cancer cases as indolent or lethal (defined as progressing to metastases and/or death)." (PMID 17726465, 2007). "Hypothetically, FDG+/PSMA- findings in prostate carcinoma patients could serve as a surrogate for MUC1 expression and, hence, for the selection of mCRPC patients that might benefit from combined MUC1 and PSMA targeted therapy." (PMID 39273701, 2024). "In addition to Sipucleucel-T vaccine, other peptide-based cancer vaccines are developed for prostate cancer, such as Cancer-associated membrane carbohydrates, including ganglioside (GM2), mucin 1 (MUC1), globo H and Thompson–Friedenreich antigen." (PMID 37654484, 2023). "This suggests that the pro-carcinogenic mechanism of MUC1 in prostate cancer may be different from other epithelial cancers such as BC, COAD, and pancreatic cancer (PAAD)." (PMID 37894512, 2023). "In addition, a direct correlation between MUC1 expression and angiogenesis has been reported in prostate cancer." (PMID 34694686, 2022). "In other studies, a high expression of MUC1 in prostate cancer and multiple myeloma may lead to a malignant phenotype." (PMID 36405691, 2022). "Similarly, following this approach, a MUC1-based autologous dendritic cell (DC) vaccine given to prostate cancer patients was reported to be safe in phase I/II studies and elicited a significant CD4+/CD8+ T cell response." (PMID 33498502, 2021). "Interestingly, Mucin 1 (MUC1) is known as a transmembrane surface protein with an altered glycosylation pattern in prostate cancer cells." (PMID 34940756, 2021). "The MUC1 was also explored as a biomarker in the electronic beacon-based prostate cancer assay." (PMID 33499136, 2021). "Similar findings have reported that sialylated MUC1 mucin plays an important role in the progression of prostate cancer and may be involved in the metastatic potential of pancreatic ductal adenocarcinoma." (PMID 32293552, 2020). "Evidence supports the upregulation of MUC1 in prostate cancer (PC)." (PMID 27825118, 2016). "Similarly, prostate cancer stem cells (PCSCs) are essential for PC progression, suggesting a relationship between MUC1 and PCSCs." (PMID 27825118, 2016). "The finding of increased MUC1 expression in cancers with adverse pathologic features suggests that MUC1 could play a role in prostate cancer progression." (PMID 27846218, 2016). "MUC1 expression has also been reported in prostate cancer metastatic to the bone." (PMID 27846218, 2016). "However, an MVA-MUC-1 vaccine induced an IFNγ+ T-cell response to MUC-1 after short-term culture in 7/34 patients with prostate cancer." (PMID 22729556, 2012). "The potential role of MUC1 in prostate cancer has been studied extensively." (PMID 19578514, 2008). "This is the first report of genetic differences in MUC1 between blood and prostatic cancer tissue." (PMID 19578514, 2008). "However, development of MUC1 as a biomarker for presence or progression of prostate cancer has been hindered by conflicting reports." (PMID 19578514, 2008). "Yet, we believe that alterations in MUC-1 expression may be useful as part of a composite set of biomarkers in accurately predicting prostate cancer outcome." (PMID 17726465, 2007). "Furthermore, although based on small numbers, our data suggest that MUC-1 expression together with Gleason grade provide substantial information to distinguish prostate cancer outcomes." (PMID 17726465, 2007). "In summary, our data show that MUC-1 is an independent prognostic marker for prostate cancer death." (PMID 17726465, 2007). "Individuals with dysregulated (either over or under) MUC-1 expression had a four- to five-fold increased risk of dying of prostate cancer, independent of clinical parameters." (PMID 17726465, 2007).